CCL20 (C-C motif chemokine ligand 20)
Diseases named in the same sentence as CCL20 in open-access papers (continued):
Sharing a sentence is not in itself a finding about the gene and the disease.
cervical squamous cell carcinoma (2 papers, 2024). A squamous cell carcinoma arising from the cervical epithelium. "In addition, Th17 and TNFRSF9high Treg were enriched and highly expressed CCL20 in advanced cervical squamous cell carcinoma." (PMID 38649887, 2024). "Specifically, CCL20+ and APOE+ macrophages with high anti-inflammatory characteristics were enriched in the advanced cervical squamous cell carcinoma." (PMID 38649887, 2024).
chronic hepatitis (2 papers, 2017 to 2024). An active inflammatory process affecting the liver for more than six months. "Accordingly, the β values for CCL20 and CXCL18 in iMac were significantly higher in patients with chronic hepatitis than those in patients with chronic infection (HBeAg− and HBeAg+)." (PMID 39135698, 2024). "It is reported that in clinics and mouse model of chronic hepatitis and fibrosis, blockade of IL-22 attenuated hepatic expression of CXC10 and CCL20 and subsequently reduced Th17 recruitment and liver inflammation and fibrosis progression." (PMID 29383167, 2017).
chronic pancreatitis (2 papers, 2010 to 2023). A chronic inflammatory process causing damage and fibrosis of the pancreatic parenchyma. "Here, we comparatively investigated the expression profile and clinical significance of the CCL20/CCR6 system in PCA as well as in chronic pancreatitis (CP) and pancreatic cystadenoma (PA) which represent pre-malignant conditions often preceding the development of PCA." (PMID 20459729, 2010). "Single-cell sequencing revealed that the CCR6/CCL20 axis is upregulated in hereditary chronic pancreatitis when compared with idiopathic chronic pancreatitis; therefore, this signaling pathway could be a potential target in human hereditary chronic pancreatitis." (PMID 37092451, 2023).
colon adenocarcinoma (2 papers, 2019 to 2021). "We observed that CCL20 and IL-17A expression in colon adenocarcinoma (COAD) and rectal adenocarcinoma (READ) tissues were higher than the expression in other cancer tissues." (PMID 31387598, 2019).
colonic diseases (2 papers, 2025). "Summarizing these results, we identified 5 proteins (CCL20, CXCL1, CXCL11, HGF, and IL-24) with increased abundance in colonic diseases, irrespective of the disease entity (colonic CD and UC) that significantly correlated with both, tissue gene expression and inflammatory severity." (PMID 40291692, 2025).
condyloma acuminatum (2 papers, 2010 to 2021). "Local hyperthermia decreases the expression of CCL-20 in condyloma acuminatum." (PMID 33710819, 2021).
dementia (2 papers, 2022 to 2024). Loss of intellectual abilities interfering with an individual's social and occupational functions. "Exceptions were the association for Beta-NGF and all-cause dementia as well as the associations of CCL3, CCL20, and IL20-RA with vascular dementia, which became statistically significant with the best fitting function." (PMID 36085081, 2022).
dermatomyositis (2 papers, 2018 to 2022). Dermatomyositis (DM) is a type of idiopathic inflammatory myopathy characterized by evocative skin lesions and symmetrical proximal muscle weakness. "CCL20 expression was found in dermatomyositis and polymyositis muscle samples and was associated with dendritic and Th17 cell homing." (PMID 30693003, 2018).
diabetic kidney disease (2 papers, 2014 to 2025). Progressive kidney disorder caused by vascular damage to the glomerular capillaries, in patients with diabetes mellitus. "Targeting pro-inflammatory chemokine CCL20 will provide novel strategy to treat diabetic kidney disease." (PMID 24733189, 2014).
dry eye (2 papers, 2013 to 2025). "Likewise, CD25-deficient mice with Sjögren-like keratoconjunctivitis sicca displayed increased CD4+ and CD8+ T cells in conjunctiva, along with elevated IL-17A and CCL20 mRNA expression in corneal and conjunctival tissues compared with wild-type mice." (PMID 41300932, 2025).
emphysema (2 papers, 2014 to 2016). "In both the COPDGene study and the TESRA study, CCL20 levels were inversely and significantly associated with emphysema although methodological considerations prevented a meta-analysis." (PMID 25306249, 2014). "Validation in the TESRA cohort revealed significant associations with RAGE, ICAM1, and CCL20 with radiologic emphysema (p < 0.001 after meta-analysis)." (PMID 25306249, 2014). "In addition, intercellular adhesion molecule 1 (ICAM1), macrophage inhibitory protein 3a (CCL20) and cadherin 1 (CDH1) were negatively associated with emphysema severity." (PMID 25306249, 2014). "Our findings, particularly when combined with other studies of individual biomarkers, suggest that a panel of blood biomarkers including sRAGE, ICAM1 and CCL20 may serve as a useful surrogate measure of emphysema and may shed light on disease pathogenesis, providing targets for new treatments." (PMID 25306249, 2014). "Regression analysis identified multiple biomarkers associated with CT-assessed emphysema in COPDGene, including advanced glycosylation end-products receptor (AGER or RAGE, p < 0.001), intercellular adhesion molecule 1 (ICAM, p < 0.001), and chemokine ligand 20 (CCL20, p < 0.001)." (PMID 25306249, 2014). "DCs, CCR6, and the severity of emphysema were significantly increased in the COPD group than in controls (all P values <0.001), and they were significantly reduced after anti-CCL20 treatment compared with the COPD group (all P values <0.05)." (PMID 27586551, 2016). "CCL20 was significantly negatively associated with emphysema in both the TESRA and COPDGene cohorts; however, meta-analysis was not possible due to CCL20 being binary in COPDGene and continuous in TESRA." (PMID 25306249, 2014). "The CCR6/CCL20 complex is one of the most potent regulators of dendritic cell migration to the lung and CCR6 knockout mice may be partially protected against cigarette smoke-induced emphysema due to reduced recruitment of inflammatory cells to the lung." (PMID 25306249, 2014). "These biomarkers (AGER, ICAM1 and CCL20) were associated with emphysema regardless of quantification technique (%LAA ≤ −950 and ≤ −910 HU and LP15A) and were replicated in an independent COPD cohort (TESRA), thus strengthening their potential utility for defining clinically relevant emphysema." (PMID 25306249, 2014). "The study confirms a previously identified association between radiologic emphysema and sRAGE, builds on data suggesting a role for ICAM1 as a biomarker, in addition to discovering previously not identified biomarkers associated with emphysema such as CCL20, cadherin 1, cadherin 13 and SERPINA7." (PMID 25306249, 2014).
epidermodysplasia verruciformis (2 papers, 2018 to 2022). A rare inherited genodermatosis characterized by chronic infection with human papillomavirus (HPV) leading to polymorphous cutaneous lesions and high risk of developing non melanoma skin cancer. "They found reduced numbers of antigen-presenting Langerhans cells in epidermodysplasia verruciformis lesions and showed the reduction to be a consequence of HPV8-mediated suppression of CCL20." (PMID 30567500, 2018).
esophageal tumor (2 papers, 2021). "Upregulation of CCL20 and CSF-3 (G-CSF) has been shown in F. nucleatum-infected esophageal tumor tissue and gingival fibroblasts, respectively." (PMID 34700376, 2021).
gallstones (2 papers, 2022 to 2025). Solid crystalline precipitates in the biliary tract, usually formed in the gallbladder, resulting in the condition of cholelithiasis. "Two studies found elevated CCL20 in patients with GBC compared to patients with gallstones, but our study is the first to show and validate an increased plasma level and potential diagnostic use of CCL20 in patients with CCA." (PMID 36699667, 2022). "For example, gallstone patients had higher levels of IL‐6, IL‐10 and IL‐12p70 than population‐based controls, and GBC patients had increased levels of C‐reactive protein (CRP), CCL20, IL‐16, sTNFRI and sTNFRII compared to gallstones controls." (PMID 39482824, 2025).
gastric adenocarcinoma (2 papers, 2021 to 2023). "In stomachs, PPARδ significantly increases chemokine Ccl20 expression in gastric epithelial cells while inducing gastric adenocarcinoma (GAC)." (PMID 37572185, 2023).
gastric MALToma (2 papers, 2014 to 2020). "Gastric specimens of patients with H. pylori-induced gastric MALToma showing detectable levels of IL-22 expression tend to have undetectable levels of CCL20 expression, suggesting an inverse association of IL-22 expression and CCL20 expression in vivo." (PMID 24824519, 2014).
hepatitis C (2 papers, 2022 to 2023). "CCL20 has been implemented as a proangiogenic factor in hepatitis C-associated HCC." (PMID 35163821, 2022).
hyperlipidemia (2 papers, 2023 to 2025). "In case of liver inflammation related genes (IL-1β, TNF-α, IL-6, IL-18, CCL20, and NF-κB) their expression levels were significantly (P < 0.05) upregulated and IL-1RN was significantly (P < 0.05) downregulated in the liver of hyperlipidemia group." (PMID 41144456, 2025). "Serum CCL20 levels are also increased in patients with hyperlipidemia." (PMID 37298199, 2023).
kidney cancer (2 papers, 2024 to 2025). Primary or metastatic malignant neoplasm involving the kidney. "Kidney cancer is part of the natural history of CKD, so longer-term studies should address a potential association with CCL20 in biological fluids." (PMID 41226600, 2025).
leprosy (2 papers, 2016 to 2018). Leprosy is a chronic infectious disease affecting primarily the skin and peripheral nervous system. "IL-23, CCL20 required for maintenance of Th17 cells and IL23R also showed enhanced expression in leprosy reactions as compared to the respective non reactive groups." (PMID 27035913, 2016). "Both types of reactions are associated with significant increase of Th17 cells and associated cytokines IL-17A, IL-17F, IL-21, IL-23 and chemokines CCL20, CCL22 as compared to matching stable forms of leprosy." (PMID 27035913, 2016).
leukaemia (2 papers, 2009 to 2022). "Res and ω-3 PUFA reduced IL-1β, IL-6, TNF-α, CXCL10/IP-10, CCL13/MCP-4 and CCL20/MIP-3α in LPS/IFN-γ activated human leukaemia THP-1 cells, which is indicative of a dampening effect on M1 macrophages." (PMID 35884829, 2022).
lichen planus (2 papers, 2020). A chronic, recurrent, pruritic inflammatory disorder of unknown etiology that affects the skin and mucus membranes. "In parallel, the increased expression of CCL20 and CCR6 has been demonstrated in lichen planus which also manifests Koebnerization." (PMID 31936670, 2020).
meningitis (2 papers, 2014 to 2025). A disorder characterized by acute inflammation of the meninges of the brain and/or spinal cord. "To confirm that CCL20 is expressed in the meningitis mouse model, we examined mouse brain homogenates from WT mice infected with S. pneumoniae." (PMID 24699535, 2014).
myositis (2 papers, 2020 to 2025). "In addition to the attention paid to CCL20, the authors of the study considered IL-17 produced by lymphocytes in the myositis muscle (in PM and DM) as a possible therapeutic target." (PMID 32775472, 2020). "Markers of type 3 inflammation were even less commonly overexpressed among the myositis groups, with exceptions being IL22RA1 in DM and CCL20 in Jo1." (PMID 40034760, 2025).
neuroblastoma (2 papers, 2022 to 2023). Neuroblastoma (NB) is the most common solid, extracranial childhood tumor. "iNKT cell infiltration is associated with CCL2 expression in neuroblastoma cells and CCL20-producing tumor-associated macrophages." (PMID 36830717, 2023). "iNKT cells infiltration in neuroblastoma is associated to CCL2 expression on tumor cells and CCL20 producing-TAMs, and iNKT cells preferentially infiltrate tumors that express high levels of this chemokine." (PMID 35615083, 2022). "The importance of the iNKT cell-TAM crosstalk is further strengthened in the same humanized neuroblastoma model, by showing that iNKT cells are recruited in the TME tumor by CCL20-producing TAMs, but are progressively inhibited in their anti-tumor activity by macrophage-induced hypoxia." (PMID 35615083, 2022).
neurosyphilis (2 papers, 2016 to 2022). Infection of the brain or spinal cord by Treponema pallidum. "Recent studies showed a significantly elevated levels of IL-8, CC chemokine ligand 20 (CCL-20) in serum, elevated levels of CXCL13, interferon(IFN)-γ in CSF, and elevated levels of IL-6, IL-10, IL-17 in both serum and CSF of neurosyphilis patients." (PMID 36203756, 2022). "CSF CCL20, CCL15 and CXCL5 levels were down-regulated in neurosyphilis patients compared to those of non-neurosyphilis patients (with at least a 0.65-fold decrease, p < 0.05)." (PMID 27650493, 2016).
oral cavity squamous cell carcinoma (2 papers, 2015 to 2019). A squamous cell carcinoma arising from the oral cavity. "In oral squamous cell carcinoma (OSCC) cells, CCL20 and FOXP3 mRNA expression is significantly correlated." (PMID 31852159, 2019).
pneumonitis (2 papers, 2023 to 2024). An inflammatory process affecting the lung parenchyma. "Thus, IL-1βhigh monocytes may recruit Th17.1 cells by expressing CXCL9/10 and CCL20, which target CXCR3 and CCR6 in ICI-pneumonitis." (PMID 36944820, 2023).
prostate tumor (2 papers, 2009 to 2025). "A CCL20-blocking antibody can significantly reduce prostate tumor growth in a mouse model by interrupting the CCL20–CCR6 interaction." (PMID 40427733, 2025). "To confirm the role of CCL20 in the development and progression of CXCR4-overexpressing prostate tumors, we evaluated the effect of neutralizing antibodies to human CCL20 on the growth of CXCR4-overexpressing PC3 cells." (PMID 19340288, 2009). "Furthermore, the treatment with anti-CCL20 antibodies inhibited the growth of CXCR4-expressing prostate tumors." (PMID 19340288, 2009). "Moreover, similar expression level of CXCR4 and CCL20 was observed on the majority of prostate tumor samples (38 out of 48 samples, 79.5%) (5B′)." (PMID 19340288, 2009). "To further study the expression pattern of CCL20 and CCR6 in prostate tumors, we stained additional specimens from 44 primary tumors." (PMID 19340288, 2009).
renal fibrosis (2 papers, 2022 to 2023). A final common manifestation of a wide variety of chronic kidney diseases characterized by glomerulosclerosis and tubulointerstitial fibrosis. "In addition, targeting CCL20 could alleviate renal fibrosis through regulating fibroblast proliferation and suppressing collagen I expression." (PMID 37287620, 2023). "Thus, targeting CCL20 by miR-143-5p could alleviate renal fibrosis progression by regulating fibroblast proliferation and ECM deposition via the Smad2/3 and AKT signaling, providing a potential therapeutic target for environmental lead contamination-evoked fibrotic kidney disease." (PMID 35485286, 2022). "Therefore, we hypothesize that CCL20 may play the potential role in renal fibrosis." (PMID 35485286, 2022).
respiratory failure (2 papers, 2020 to 2024). The significant impairment of gas exchange within the lungs resulting in hypoxia, hypercarbia, or both, to the extent that organ tissue perfusion is severely compromised. "Besides expression of pro-inflammatory cytokines, such as IL-1β and TNF-α, the expression of chemokines CCL2, CCL3, CCL20, CXCL1, CXCL3, CXCL10, IL-8 was shown likely to contribute to clinical observation of excessive inflammatory tissue damage, lung injury, and respiratory failure." (PMID 33362782, 2020).
retinal degeneration (2 papers, 2019 to 2023). Degeneration of the retina. "Treatment with CCL20-neutralizing antibodies or PG inhibits CCL20 expression, alleviating retinal degeneration and inflammation." (PMID 36658547, 2023). "rTBI induced cerebral neurodegeneration, retinal degeneration, microgliosis, astrogliosis, and CCL20 expression." (PMID 31151410, 2019). "Treatment with CCL20 neutralization antibody or PG showed reduced CCL20 expression along with reduced retinal degeneration and inflammation." (PMID 31151410, 2019).
subarachnoid hemorrhage (2 papers, 2020 to 2021). A serious neurological disorder characterized by intracranial hemorrhage into the subarachnoid space. "Recent evidence suggests that CC chemokine ligand 20 (CCL20) is upregulated after subarachnoid hemorrhage (SAH)." (PMID 32575072, 2020).
systemic sclerosis (2 papers, 2021 to 2024). A chronic disorder, possibly autoimmune, marked by excessive production of collagen which results in hardening and thickening of body tissues. "We have recently demonstrated that serum CCL20 levels positively correlate with mean pulmonary arterial pressure in patients with systemic sclerosis (SSc)." (PMID 34774095, 2021). "Additionally, a positive correlation of CCL20 serum levels and mPAP in systemic sclerosis patients was observed." (PMID 38247549, 2024).
thymic carcinoma (2 papers, 2023 to 2024). Thymic carcinoma (TC) is a type of thymic epithelial neoplasm characterized by a high malignant potential. "For thymic carcinoma, the novel biomarkers of MSLN, CCL20, and SLC1A5 are identified and observed an elevated expression of LAG3 and HAVCR2 in malignant tumorn‐infiltrating mature T cells." (PMID 39258580, 2024).
viral meningitis (2 papers, 2014 to 2019). Inflammation of the membranes surrounding the brain and spinal cord due to a viral infection. "Both, bacterial and viral meningitis additionally displayed significantly elevated concentrations of the cytokines CCL1, CCL19, CCL20, CXCL2, CXCL6, IFNγ, and IL16." (PMID 31727097, 2019).
acne (1 paper, 2014). An inflammatory process of the sebaceous glands which is characterized by comedones, nodules, papules and/or pustules on the skin. "Furthermore, Th17 cell products IL-17A, IL-22, IL-26, TNF and IL-17 induced chemokines CSF2 and CCL20 were also expressed at higher levels in acne lesions." (PMID 25153527, 2014). "The expression of cytokines IL-6, IL-12p40, INF-γ and TGF-β have not been studied earlier in acne lesions as also noticed by Thiboutot and co-workers, nor cytokines IL-17A, IL-17F, IL-23p19, IL-22 and chemokines CCL20 and CSF2." (PMID 25153527, 2014).
acrodermatitis chronica atrophicans (1 paper, 2017). An acrodermatitis characterized by a chronically progressive course, leading to widespread atrophy of the skin. "IL-17A, CXCL1 and CCL20 have however been reported present in other Lyme borreliosis manifestations, such as Lyme arthritis (IL-17), erythema migrans and acrodermatitis chronica atrophicans (CXCL1 and CCL20)." (PMID 28148307, 2017).
alcoholic liver diseases (1 paper, 2018). A disorder caused by damage to the liver parenchyma due to alcohol consumption. "CCL20 also appears to play a key role in alcoholic liver disease, as well an emerging role in viral hepatitis." (PMID 29690903, 2018). "In studies of alcoholic liver disease closely paralleling those reported here, CCL20 was found to be the most up-regulated chemokine gene by microarray gene expression profiling of human liver biopsy tissue." (PMID 29690903, 2018). "An important aspect of our results, similar to those for the role of CCL20 in alcoholic liver disease, is the use of ex vivo human samples and cultured human cell lines to define the transcriptional regulation of the CCL20 gene in HSCs, which has not yet been well characterized in vivo." (PMID 29690903, 2018). "CCL20 may also be a common pathogenetic mediator in both non-alcoholic and alcoholic liver disease." (PMID 29690903, 2018).
arteriosclerosis (1 paper, 2023). A vascular disorder characterized by thickening and hardening of the walls of the arteries. "Overexpression of serine protease inhibitor, clade E member 1 (SERPINE1), Toll-like receptor 2 (TLR2), and CC Chemokine ligand 20 (CCL20) were also reported as a significant causative factors in the progression of arteriosclerosis, thrombosis, differentiation of SMCs and perivascular fibrosis." (PMID 37373979, 2023).
B cell lymphoma (1 paper, 2023). "inoculation of murine A20 B cell lymphoma cells) contributed to the local SLC-mediated release of human CXCL16 and CCL20." (PMID 37185750, 2023).